MARCHF10 (membrane associated ring-CH-type finger 10)
Description:
E3 ubiquitin-protein ligase (Probable). E3 ubiquitin ligases accept ubiquitin from an E2 ubiquitin-conjugating enzyme in the form of a thioester and then directly transfer the ubiquitin to targeted substrates.
Synonyms: MARCH-X; MARCH10; RNF190; FLJ35757
Tractability: Antibody: the Human Protein Atlas places it where antibodies can reach.
Gene: Protein-coding gene on chromosome 17 (62,701,314 to 62,808,344, reverse strand). Ensembl gene ENSG00000173838.
Subcellular location (Human Protein Atlas): Cytosol; Plasma membrane
Gene Ontology:
Molecular function: protein binding; ubiquitin protein ligase activity; zinc ion binding
Biological process: protein ubiquitination
Genetic constraint (gnomAD): Loss-of-function variants: 63 observed, 83.36 expected, observed/expected ratio (o/e) 0.76, 90% interval 0.62 to 0.93. The upper end of that interval is the gene's LOEUF score, 0.93, which puts it in group 3 of 6, group 1 being the genes least tolerant of losing a copy. Missense variants: 875 observed, 1,011.1 expected, observed/expected ratio (o/e) 0.87, 90% interval 0.82 to 0.92. Synonymous variants: 340 observed, 378.89 expected, observed/expected ratio (o/e) 0.9, 90% interval 0.82 to 0.98.
Homologues: Orthologues: chimpanzee MARCHF10 (98% identical), macaque MARCHF10 (91% identical), dog MARCHF10 (74% identical), pig MARCHF10 (70% identical), mouse Marchf10 (62% identical), rat Marchf10 (62% identical), rabbit MARCHF10 (62% identical), guinea pig MARCHF10 (61% identical), tropical clawed frog marchf10 (21% identical). Paralogues in human: MARCHF7 (21% identical).
Diseases named in the same sentence as MARCHF10 in open-access papers:
MARCHF10 is named in the same sentence as 6 diseases in open-access papers, as found by Europe PMC text mining. Sharing a sentence is not in itself a finding about the gene and the disease. The quoted sentences say what the papers report.
cardiomyopathy (1 paper, 2022). A disease of the heart muscle or myocardium proper. "In MARCHF10, rs199705946 suggestively associated with lower phospholipid concentrations in the VLDL particles (p=0.07) was exclusively found in the Finnish population with MAF of 0.3%, predicted deleterious by SIFT and PolyPhen-2, and was associated with cardiomyopathy (p=3.40×10−5, OR=3.7)." (PMID 36419110, 2022).
MARCHF10 also shares sentences with these, for which no sentence is quoted: breast carcinoma (1 paper); breast tumors (1); lung adenocarcinoma (1); lung squamous cell carcinoma (1); tauopathy (1).